CDK4 (cyclin dependent kinase 4)
Diseases named in the same sentence as CDK4 in open-access papers (continued):
Sharing a sentence is not in itself a finding about the gene and the disease.
tumor (continued). "We show that combining a RAS(ON) multi-selective inhibitor with the CDK4/6 inhibitor palbociclib drives persister cells into a senescent-like state, which coincides with improved tumor control and substantial remodeling of the tumor microenvironment." (PMID 40299790, 2025). "The monarcHER and PATRICIA trial indicates that inhibiting CDK4/6 could bolster the longevity of anti-tumor effects elicited by the concurrent use of HER2-targeted." (PMID 40743286, 2025). "Although combination therapies are typically administered simultaneously, the “priming strategy” using CDK4/6 inhibitors—short‐term pretreatment to synchronize tumor cell cycles and enhance sensitivity to subsequent therapies—has emerged as a focus in HNSCC clinical research." (PMID 40936164, 2025). "CDK4/6i drives tumor cells to secrete MIF by activating the HIF-1α pathway." (PMID 41082324, 2025). "Furthermore, our novel in vivo model of acquired resistance to CDK4/6i is unique, being characterized by tumor response to continuous CDK4/6 inhibition before the eventual emergence of resistance in the absence of new driver mutations." (PMID 38047585, 2024). "Moreover, combined CDK4/6-MEK therapy was previously shown to activate CD8+ T cell or natural killer (NK) cell-mediated immune responses in other tumor types." (PMID 39347707, 2024). "For example, the regulation of CENPA could affect CCND1 and CDK4/6, interfering with cell cycle, and also affect the activity of the Wnt signalling pathway, ultimately affecting the proliferation and growth of tumour cells." (PMID 39620895, 2024). "The genomic landscape of baseline tumor biopsies in this trial spanned the spectrum of genes and pathways (RTK, MAPK, PI3K/AKT/mTOR, cell cycle, and ER pathways) known to be associated with resistance to CDK4/6 inhibitors and endocrine therapy." (PMID 38503755, 2024). "Intriguingly, elevated tumor cell antigen presentation combined with anti-tumor T cell responses shows that CDK4/6 inhibitors may increase response to ICIs for tumors." (PMID 38822443, 2024). "It's worth noting that CDK4/6 inhibitors like ribociclib block the process of tumor cells entering the S/M period of the cell cycle, which may affect the efficacy of T-DM1." (PMID 39093344, 2024). "Novel inhibitors of these targets, alone or in combination, may overcome CDK4/6 inhibitor resistance, induce synthetic lethality and sensitise tumours to immunotherapy." (PMID 38264947, 2024). "Importantly, the growth kinetics was increased in Hgf-Cdk4 mice when compared to Cdk4 mice, leading to increased tumor penetrance and significantly shorter survival." (PMID 38360887, 2024). "However, the impact of CDK4/6i on circulating immune cells and circulating tumor cells (CTCs) in patients receiving CDK4/6i and ET (CDK4/6i+ET) remains poorly understood." (PMID 39195280, 2024). "Inhibition of CDK4/6 has been shown to favour the elimination of tumour cells by the adaptive immune system through various mechanisms including enhanced antigen presentation by cancer cells, increased infiltration and activation of T cells; and inhibition of regulatory T cells proliferation." (PMID 36453028, 2024). "The study involving 213 MM tumor samples taken from Chinese patients indicated that CDK4 inhibitors may arrest tumor proliferation through various signaling pathways." (PMID 39598629, 2024). "The primary mechanism of CDK4/6i resistance in tumor is RB inactivation." (PMID 39139449, 2024). "Among them, Cdk4/6, an important target for tumor therapy, has shown significant efficacy in late-stage metastatic breast cancer, particularly for HR + and Her2-subtypes, with the clinical application of inhibitors such as palbociclib, ribociclib, and abemaciclib." (PMID 38701314, 2024). "The three tumor clusters highly expressed CDK4, CCND1, and MYCN, respectively." (PMID 38181797, 2024).
tumor (continued). "In order to investigate the impact of the HER4 receptor on tumor growth and in the context of anti-hormonal and CDK4/6i therapy, humanized mice were transplanted with MCF-7 WT and MCF-7 HER4 knockout cells and treated with tamoxifen and abemaciclib, respectively." (PMID 39000582, 2024). "To test the hypothesis that CDK4 inhibitors could target MM with CDK4 amplification, we first assessed the anti-tumor activity of dalpiciclib via HNMM PDX and PDC models." (PMID 38807144, 2024). "Among the 425 patients with the information on the CDK4/6i treatment before biopsies collection and the CDK4 amplification status, 69 have been tested (when RNA was available) for CDK4 expression by a real-time quantitative RT-PCR: 3 CDK4-amplified tumours and 66 CDK4-unamplifified tumours." (PMID 39090361, 2024). "The combination of CDK4/6i and A80.2HCl result in marked regression in tumor growth in vivo." (PMID 38424044, 2024). "Notably, it has recently been suggested that CDK4/6is are also able to alter the tumor microenvironment (TME), which is suggested to play a double-faced role in patients treated with CDK4/6is." (PMID 39593745, 2024). "Additionally, when possible, we acquired archival tumor biopsies that preceded the patient’s initial exposure to a CDK4/6i to serve as a CDK4/6i-naive sample." (PMID 38503755, 2024). "This subset of patients may exhibit aggressive tumor behaviors or have been heavily pretreated, potentially leading to resistance to CDK4/6i." (PMID 39133334, 2024). "Knocking down either KLHL42 or MYC-sensitized tumor cells to CDK4/6i treatment." (PMID 38424044, 2024). "Taken together, these results indicate that engineered genetic disruptions in protein assemblies identified by NeST-VNN can influence tumor cell growth in the setting of CDK4/6 inhibition, whether such inhibition is induced by a drug or CDK4/6 KO." (PMID 38443662, 2024). "In univariate analysis, neither mPFS nor mOS was associated with age, tumor grade, receptor status, Ki67 status, time from diagnosis to CDK4/6i cessation, therapy line, or CDK4/6i type." (PMID 39199665, 2024). "Although the bulk tumor cell mass was effectively killed by dual EZH2/CDK4/6 blockade, our flow cytometric approach may have missed or unidentified potential effects on this rare subpopulation." (PMID 39054369, 2024). "Based on these and additional features, we asked whether these known and plausible resistance mechanisms could explain each baseline tumor’s resistance to prior CDK4/6i and antiestrogen treatments." (PMID 38503755, 2024). "Vehicle treatment (i.e., withdrawal of abemaciclib) led to acceleration of tumor growth accompanied by increased tumor cell proliferation and Rb phosphorylation, consistent with the notion that CDK4/6i continue to play some antiproliferative role in these tumors, even in the setting of resistance." (PMID 38047585, 2024). "In addition, considering the role of VEGF in inhibiting anti‐tumor immunity, senescent cancer cells induced by DNA‐damaging agents can promote a more potent pro‐tumorigenic immune microenvironment than CDK4/6i." (PMID 37854019, 2024). "Moreover, the combined application of oncolytic adenovirus XVir-N-31, driven by YB-1, with CDK4/6 inhibitors, is observed to facilitate the maturation of monocyte-derived DCs, thus increasing their capacity in activating tumor antigen-specific T cells." (PMID 38915446, 2024). "Selective inhibition of CDK4 has also demonstrated efficacy in tumor treatment." (PMID 38528618, 2024). "This examines complementary mechanisms since anti-CD200 therapies deplete immunosuppressive signals within the tumor microenvironment and amplify immune-mediated tumor attacks, while CDK4/6 inhibitors block tumor proliferation via the induction of G1 cell cycle arrest." (PMID 39795972, 2024).
tumor (continued). "Notably, the triple combination exhibited more pronounced effects on HER2 mRNA and protein expression levels in tumor tissues compared with CDK4/6 inhibitor combined with endocrine therapy alone (P < 0.01)." (PMID 39730704, 2024). "Cyclin D1 then partners with CDK4/6 to stimulate tumor cell proliferation." (PMID 39858553, 2024). "Whereas it was absent in normal pleura, CDK4 phosphorylation was detected with variable abundance in 39 of 47 tumours, suggesting that about 80% of patients could respond to CDK4/6 inhibition." (PMID 36453028, 2024). "Notably, dual EZH2/CDK4/6 blockade also reduced 3D-spheroid invasion, partially inhibited tumor growth in ovo, and led to impaired viability of patient-derived organoids." (PMID 39054369, 2024). "When CDK4 phosphorylation was detected, its relative abundance significantly correlated with the ‘Cell Cycle Proliferation’ score calculated from RNA‐seq data, which was significantly different in class H versus class L tumours." (PMID 36453028, 2024). "In a recent study, a CRISPR-CAS9 loss of function screen revealed a spectrum of functional genes whose inhibition might complement the tumor inhibition properties of CDK4/6 inhibitors in PDAC, in which HDAC genes were identified as positive hits." (PMID 39123441, 2024). "For instance, inhibition of CDK4/6 enhances tumor cell immunogenicity through multiple mechanisms." (PMID 38605349, 2024). "Of note, this CDK4/6 inhibitor was less effective when BC cells were co-cultured with CAFs, in accordance with previous findings indicating that fibroblasts may alter tumor responses to chemotherapeutics." (PMID 38886784, 2024). "However, objective tumor response is observed in <50% of patients who receive CDK4/6 inhibitors as first-line therapy, and nearly all initially responsive patients develop drug resistance with subsequent mortality." (PMID 38443662, 2024). "Therefore, for the frailest ABC patients with a low disease burden and few tumor symptoms, we suggest starting with ET alone and introducing a CDK4/6i upon progression." (PMID 38791919, 2024). "Our results showed that 3 CDK4-amplified tumours were among the 4 most CDK4-overexpressed tumours." (PMID 39090361, 2024). "Thus, targeting the CDK4/6 pathway in tumor-infiltrated T cells holds promise for enhancing the efficacy of anti-tumor immunotherapy." (PMID 38750022, 2024). "Currently, IHC of MDM2 and CDK4 may help screen for 12q13-15 amplification, which is seen in dedifferentiated tumours." (PMID 39011191, 2024). "Recent studies suggest that CDK4/6 inhibition stimulates the anti-tumor immune response." (PMID 38927958, 2024). "Interestingly, the tumour with the highest degree of CDK4 phosphorylation (E3, a patient who died 2 months after diagnosis) presented also an elevated CDKN2A mRNA expression, but its p16 staining was weak." (PMID 36453028, 2024). "In addition, in the current era of CDK4/6 inhibitors, the activity of fulvestrant on ER-positive breast cancer (both the wild-type ESR1 and the ESR1 mutant) after tumor progression on CDK4/6 inhibitors appears limited." (PMID 38339371, 2024). "During first-line treatment with a CDK4/6i + ET, the early onset of ESR1 mutations detected in circulating tumor DNA (ctDNA) could direct a switch strategy including modification of the endocrine backbone." (PMID 38930141, 2024). "Further studies are needed to understand the effect of CDK4/6 inhibition on the tumor cells and microenvironment, an effect which may vary according to tumor subtypes." (PMID 38448600, 2024). "CDK4 T172‐phosphorylation might thus be the best biomarker of potential tumour sensitivity to CDK4/6i." (PMID 36453028, 2024). "This clinical trial evaluating the benefit of continued CDK4/6 therapy after progression on a prior CDK4/6 inhibitor is to our knowledge unique in having carried out in-depth multi-omic tumor analysis in baseline metastatic tissue and blood samples taken after development of CDK4/6i resistance." (PMID 38503755, 2024).
tumor (continued). "We detected CDK4 phosphorylation in 80% of MPM tumours suggesting that the majority of the patients could at least initially respond to CDK4/6i." (PMID 36453028, 2024). "For each patient, it includes whether these features could explain if the baseline tumor is resistant to prior CDK4/6i and antiestrogen treatments, and if these are known or plausible resistance mechanisms." (PMID 38503755, 2024). "The study demonstrated that EC could be one of the sensitive tumor types, as CDK4 was shown to have higher expression compared to CDK6 in various reproductive organ systems, where abemaciclib has a higher potency against CDK4 compared to CDK6." (PMID 39330025, 2024). "Mounting preclinical evidence indicates that CDK4/6i sensitise in vitro and in vivo models to anti‐PD‐1 blockade, mainly via stimulation of tumour cell antigen presentation, inhibition of the proliferative capacity of T regulatory cells and increase of T cell inflammatory signatures." (PMID 38264947, 2024). "Unexpectedly, CDK4 phosphorylation was undetectable in six proliferative tumours." (PMID 36453028, 2024). "Interestingly, several studies have demonstrated that CDK4/6–cyclin D1 also regulates the function and development of immune cells in the tumor microenvironment." (PMID 39593745, 2024). "To test whether this association holds in recurrent tumors, we calculated the odds ratio (OR) for co-amplification of EGFR and CDK4 for each tumor." (PMID 38805346, 2024). "In one of these patients, each tumor lineage acquired a genomic alteration in HER2 (ERBB2 amplification, ERBB2L755S mutation), demonstrating convergent evolution of ERBB2 activation following CDK4/6i therapy." (PMID 38503755, 2024). "Taken together, these findings suggest that DNA‐damaging agent‐induced senescence can promote tumor angiogenesis via secretion of pro‐angiogenic factors, while CDK4/6i‐induced senescence can inhibit angiogenesis through regulation of anti‐angiogenic factors in the TME." (PMID 37854019, 2024). "Moreover, CDK4/6 inhibitors are currently being explored for other tumor types, and these are each likely to have novel resistance mechanisms." (PMID 38562687, 2024). "Although no non-canonical tumor-promoting role of p18INK4c was identified, p18INK4c is implicated in contributing to resistance to CDK4/6 inhibitors." (PMID 38561743, 2024). "Additionally, our preclinical results have demonstrated robust anti-tumor effects of CDK 4/6 inhibitor in HNMM patient-derived xenograft models with CDK4 amplification." (PMID 38807144, 2024). "This dual effect suggests a complex dynamic where CDK4/6 inhibitors may enhance the immune recognition of tumor cells but limit the expansion of T cell populations, potentially influencing the overall effectiveness of immune responses during treatment." (PMID 39797256, 2024). "Interestingly, both the CDK4/6 inhibitor + endocrine therapy and triple combination groups displayed significant inhibition of tumor growth compared with the control group (P < 0.05)." (PMID 39730704, 2024). "For 22 out of 23 patients with WES and/or RNA-seq of a baseline biopsy (n = 22/23, 96%), we identified genomic or transcriptomic features that could explain the tumor’s resistance to CDK4/6i or anti-ER treatments." (PMID 38503755, 2024). "We also found that the shared copy number variants (CNVs) between CSF and tumor tissue, including PDGFRA, MDM2, CDK4, and others, were exclusively observed in DMG, H3K27-altered, and the copy number value of shared CNVs showed a strong correlation between CSF and tissue." (PMID 38388726, 2024). "Inhibition of either CDK4 or PIN1 has been reported to trigger anti-tumor immunity." (PMID 38622115, 2024). "CDK4, a member of the cell-cycle-dependent kinase protein family, positively regulates cell cycle regulatory factors, inducing rapid transition from G1 phase to S phase and promoting tumor growth." (PMID 39336799, 2024).
tumor (continued). "Future studies investigating the biological behavior of each CDK4/6 are warranted to understand how possible differences in drug–tumor interaction between those agents may lead to variations in RCTs results." (PMID 38793046, 2024). "The mechanism of BEZ235-induced autophagic degradation of CDK4 has also been established in other tumor cell models, such as SK-N-MC, and NB cells like SH-SY5Y, which shows that the mechanism of autophagic degradation of CDK4 induced by BEZ235 is reliable and applicable." (PMID 39087955, 2024). "It is, therefore, still interesting to investigate whether senescent cancer cells induced by CDK4/6i treatment have a stronger ability to create the anti‐tumor immune microenvironment compared to other conventional chemotherapeutic DNA‐damaging agents." (PMID 37854019, 2024). "Dysregulated CDK4 contributes to abnormal cell proliferation and tumor development." (PMID 37460940, 2023). "Given its robust overall response rate (50% to 60% in the first line), the CDK4/6i and AI may be considered even when rapid tumor response is needed, although chemotherapy remains a gold standard in case of visceral crisis." (PMID 37759823, 2023). "Recent research has shown that CDK4/6 exhibit substantial cell cycle independent activity in tumour immunosurveillance, and CDK4/6 inhibitors may control the immune system response to tumour cells." (PMID 36768557, 2023). "First, newly available information suggests that CDK4/6 inhibitors may have an immediate immunomodulatory effect on tumour cells." (PMID 36768557, 2023). "In contrast, Cdk4−/−/Mavs−/− tumor grew at slower rates similar as Cdk4−/− tumors." (PMID 37833461, 2023). "This work reveals a function of both LRPPRC and CDK6 in tumor development and CDK4/6i resistance." (PMID 37452037, 2023). "However, CDKN2B, also known as p15, is another critical tumor suppressor, which inhibits cyclin kinases CDK4 and CDK6." (PMID 36952446, 2023). "Of note, patients with mRNA tumor expression of CDK4 higher than the median value had a tendency to a longer median PFS [(5.23 months, 95% CI 3.04–7.43) vs. (1.90 months, 95% CI 0.64–3.16), p = 0.11] and OS [(15.53 months, 95% CI 8.99–22.09) vs. (10.57 months, 95% CI 0.0–23.19), p = 0.098]." (PMID 37875500, 2023). "NF-κB and PD-L1 could be suppressed by CDK4/6-phosphorylated RB protein, which is a well-studied tumor suppressor, thus eliminating tumor development, and this seems to be a common regulatory mechanism occurring in different tumor types." (PMID 37375731, 2023). "Resistance to CDK4/6 inhibitors may induce the activation of signaling pathways independent of CDK4/6 or increase the CDK4/6 inhibition threshold, leading to sustained tumor." (PMID 36978140, 2023). "The inhibition of CDK4/6 could trigger anti-tumor immunity, and a preclinical study showed that combining CDK4/6 inhibitor plus PI3K inhibitor with ICIs in TNBC murine model induced a long-lasting tumor regression." (PMID 37345194, 2023). "Still, the use of palbociclib (a CDK4/6 inhibitor) associated with omipalisib (a PI3K/mTOR dual inhibitor) in ATC in vitro and in vivo models significantly reduced cell proliferation in cell lines and inhibited tumor growth in lower doses." (PMID 38139812, 2023). "Moreover, recent evidence demonstrate that CDK4/6 inhibitors enhance tumor immunogenicity through potential elimination of tumor cells, providing an explanation for new combination therapies involving CDK4/6 inhibitors and immunotherapy." (PMID 37228871, 2023). "These resistant tumors demonstrated post-treatment enrichment of CDK4; subsequent in vivo CDK4/6 inhibition potentiated anti-PD-1 therapy in these treatment-resistant cells, resulting in decreased tumor growth and greater T-cell infiltration than anti-PD-1 therapy alone." (PMID 37046760, 2023). "Furthermore, the expression of the proliferation marker Ki67, and the cell cycle markers CDK2, CDK4, and CyclinD1 was analyzed through immunohistochemical detection of tumor samples." (PMID 38027998, 2023).